PRDX1 (peroxiredoxin 1)
Diseases named in the same sentence as PRDX1 in open-access papers (continued):
Sharing a sentence is not in itself a finding about the gene and the disease.
influenza (1 paper, 2018). An acute viral infection of the respiratory tract, occurring in isolated cases, in epidemics, or in pandemics; it is caused by serologically different strains of viruses (influenzaviruses) designated A, B, and C, has a 3-day incubation period, and usually lasts for 3 to 10 days. "The densitometric analysis of ratio PRDX1/actin of three animals for each sex at 3 and 6 days p.i. was 1.5- and 3-fold higher, respectively, unpaired t-test *p-value ≤0.05, suggesting that females are more protected by influenza for the presence of reducing conditions." (PMID 30105026, 2018).
intracerebral hemorrhage (1 paper, 2023). A cerebrovascular disorder characterized by bleeding into one or both cerebral hemispheres including the basal ganglia and the cerebral cortex. "Moreover, Prdx1 is also known as an important RNA-binding protein engaged in regulating inflammatory response and apoptosis in intracerebral hemorrhage rat models." (PMID 37886002, 2023).
Intraductal papillary mucinous neoplasm (1 paper, 2017). "To determine if changes in Prdx1, Txn, and Srxn expression correlate with changes observed in early stage disease, we employed mouse models of pancreatic neoplasia resembling PanIN (Pancreatic intraepithelial neoplasia) and IMPN (Intraductal papillary mucinous neoplasm)." (PMID 29190947, 2017).
liver fibrosis (1 paper, 2017). "Furthermore, CAT, BLVRB, NXN, PRDX1, and IDH1 may be candidates for the detection of liver fibrosis or therapeutic targets for the treatment of liver fibrosis." (PMID 28830339, 2017). "Furthermore, CAT, BLVRB, NXN, PRDX1, and IDH1 may be candidates for detection of liver fibrosis or therapeutic targets for the treatment of liver fibrosis." (PMID 28830339, 2017).
lower respiratory tract infection (1 paper, 2019). "It is noteworthy that PRDX1 has been implicated in respiratory syncytial virus (RSV), a lower respiratory tract infection that is often associated with influenza virus." (PMID 31159726, 2019).
lung diseases (1 paper, 2023). "Changes in cellular redox status have been found to be associated numerous lung diseases, and PRDX1 expression is elevated in the lung tissues of patients with pulmonary fibrosis." (PMID 37268886, 2023). "PRDX1 can remove excessive cellular ROS and is involved in the occurrence and development of several lung diseases." (PMID 37268886, 2023).
lung fibrosis (1 paper, 2023). "Further, to assess the molecular mechanism underlying the role of PRDX1 in BLM-induced pulmonary fibrosis in mice, the expression levels of fibrosis-related proteins were determined by western blot analysis." (PMID 37268886, 2023). "In the process of BLM-induced pulmonary fibrosis, PRDX1-knockout (KO) mice produce more severe pulmonary inflammation and pulmonary fibrosis." (PMID 37268886, 2023). "BLM induces more severe pulmonary fibrosis in PRDX1-KO mice as well as a strong activation of PI3K/AKT and JNK/Smad signalling pathways." (PMID 37268886, 2023). "Our observations strongly suggest the important role of AKT/PI3K and JNK/Smad signalling pathways in the regulation of pulmonary fibrosis by PRDX1." (PMID 37268886, 2023). "BLM treatment induced more severe pulmonary fibrosis in PRDX1-knockout mice, mainly through the PI3K/Akt and JNK/Smad signalling pathways." (PMID 37268886, 2023). "PRDX1 has been demonstrated to regulate TGF-β-induced EMT through its antioxidant activity, pointing to the possibility that PRDX1 can participate in the TGF-β-induced EMT through its antioxidant activity in BLM-induced pulmonary fibrosis as well." (PMID 37268886, 2023). "Therefore, PRDX1 is of great interest for the research on the occurrence and development of pulmonary fibrosis." (PMID 37268886, 2023). "Significant changes in the levels of EMT-related proteins were detected in lung fibrosis tissues of BLM-treated PRDX1-KO mice, accompanied by significant changes in the expression of proteins involved in cell cycle and fibrosis, and a more severe process of pulmonary fibrosis was observed." (PMID 37268886, 2023). "Moreover, PRDX1 deficiency significantly promoted the proliferation of pulmonary fibroblasts and the secretion of collagen by increasing the activation of the PI3K/Akt and JNK/Smad signalling pathways, further exacerbating pulmonary fibrosis." (PMID 37268886, 2023). "Therefore, in this study, we further explored the role of PRDX1 in BLM-induced pulmonary fibrosis." (PMID 37268886, 2023). "Therefore, whether PRDX1 can regulate the process of pulmonary fibrosis through ER stress needs further exploration." (PMID 37268886, 2023). "In this study, the knockdown of PRDX1 induced a significant increase in ROS levels in lung epithelial cells and in the mitochondria, accompanied by mitochondrial damage, which laid the groundwork for ROS-induced damage to lung epithelial cells and triggered pulmonary fibrosis." (PMID 37268886, 2023). "However, further exploration is needed to determine whether PRDX1 can regulate fibroblast fibrosis to affect the development of pulmonary fibrosis." (PMID 37268886, 2023). "Although it has been found that PRDX1 has an impact on the development of pulmonary fibrosis, the role of PRDX1 in BLM-induced pulmonary fibrosis remains elusive." (PMID 37268886, 2023). "PRDX1 knockout resulted in an increase in AKT/PI3K and JNK/Smad phosphorylation levels in BLM-induced pulmonary fibrosis tissues in mice." (PMID 37268886, 2023). "In pulmonary fibroblasts, PRDX1 knockdown significantly increases cellular proliferation and induces the secretion of collagen by promoting the activation of the PI3K/AKT and the JNK/Smad signalling pathways, further exacerbating pulmonary fibrosis." (PMID 37268886, 2023). "Moreover, as examined by H&E staining, the lungs of PRDX1-KO mice produced more severe pulmonary fibrosis; the other organs exhibited no significant changes." (PMID 37268886, 2023). "Our findings strongly suggest that PRDX1 is a key molecule in BLM-induced lung fibrosis progression and acts through modulating EMT and lung fibroblast proliferation; therefore, it may be a therapeutic target for the treatment of BLM-induced lung fibrosis." (PMID 37268886, 2023). "However, it is currently not clear whether PRDX1 regulates the proliferation ability of fibroblasts through the JNK/Smad pathway, thereby affecting the development of pulmonary fibrosis." (PMID 37268886, 2023).
medulloblastoma (1 paper, 2019). A malignant, invasive embryonal neoplasm arising from the cerebellum. "Concurrent administration of HAV6 peptide with Ade, a BBB impermeable inhibitor of Peroxiredoxin-1, caused reduced tumor growth and increased survival in mice bearing medulloblastoma." (PMID 31533285, 2019).
Methylmalonic aciduria (1 paper, 2025). Increased concentration of methylmalonic acid in the urine. "It is worth noting that genetic testing for methylmalonic acidurias must consider epi-cblC, and pathogenic variants must be searched for in MMACHC and PRDX1." (PMID 40565527, 2025).
myeloid leukemia (1 paper, 2025). A clonal proliferation of myeloid cells and their precursors in the bone marrow, peripheral blood, and spleen. "PRDX1 expression was significantly elevated in myeloid leukemia cells compared to normal white blood cells, with even higher levels observed in samples from patients who failed to respond to induction therapy." (PMID 40825764, 2025). "To investigate the role of PRDX1 in myeloid leukemia, we analyzed publicly available datasets." (PMID 40825764, 2025).
myocardial ischemia (1 paper, 2020). A disorder of cardiac function caused by insufficient blood flow to the muscle tissue of the heart. "Another study also showed that Prdx1 overexpression alleviates cardiomyocyte apoptosis by scavenging ROS during myocardial ischemia/reperfusion injury." (PMID 32802259, 2020).
nasopharyngeal carcinoma (1 paper, 2023). A carcinoma arising from the nasopharyngeal epithelium. "PRDX1 has been shown to repress nasopharyngeal carcinoma cell proliferation, migration, invasion, and epithelial-mesenchymal transition in vitro by inactivating the PI3K/AKT/TRAF1 pathway." (PMID 37227568, 2023).
neuroblastoma (1 paper, 2021). Neuroblastoma (NB) is the most common solid, extracranial childhood tumor. "PDIA3 identified following from DAT of MPN was found to be directly interacting with PRDX1 (found in both DAT of MPN and DMT of neuroblastoma cells), ACTB (found in DAT of MPN and both in DAT and DMT of neuroblastoma cells), and HSPD1." (PMID 34394070, 2021).
nonalcoholic steatohepatitis (1 paper, 2025). "Additionally, it has been shown that rosemarinic acid (RA), another antioxidant, specifically enhances the enzymatic activity of peroxidase 1 (PRDX1), thus alleviating nonalcoholic steatohepatitis (NASH)." (PMID 41049367, 2025).
ovarian tumors (1 paper, 2025). "PRDX1 interacted with the MRN complex, and we previously showed that high MRE11 expression in ovarian tumors is linked to an aggressive phenotype and predicts platinum resistance." (PMID 40387816, 2025).
periodontitis (1 paper, 2018). An acute or chronic inflammatory process that affects the tissues that surround and support the teeth. "LPS challenge contributes to the production of reactive oxygen species (ROS) in periodontitis, and peroxiredoxin 1 (Prx1) is an antioxidant protein that protect cells against oxidative damage from ROS." (PMID 29707240, 2018).
preeclampsia (1 paper, 2023). Preeclampsia is a hypertensive disorder of pregnancy that is characterized by new-onset hypertension with proteinuria presenting after 20 weeks of gestation, and depending on mild or severe forms may initially present with severe headache, visual disturbances, and hyperreflexia. "The aim of this study is to investigate the effect of PRDX1 on the regulation of trophoblast function by affecting autophagy and oxidative stress in preeclampsia." (PMID 37227568, 2023).
prion disease (1 paper, 2015). A transmissible disease that is caused by a protein that is able to induce abnormal folding of normal cellular proteins, leading to characteristic spongiform brain changes, which are associated with neuronal loss without an inflammatory response. "Similarly, GFAP, tubulin, peroxiredoxin 1, cofilin-1, and alpha/gamma enolase are selectively citrullinated in prion disease." (PMID 26441823, 2015).
psoriasis (1 paper, 2022). An autoimmune condition characterized by red, well-delineated plaques with silvery scales that are usually on the extensor surfaces and scalp. "We found that Prdx1 expression was upregulated in IMQ-induced psoriasis-like mice and MRL/lpr mice after treatment with sulforaphane, suggesting that sulforaphane exerted the antioxidant effects dependent on the activation of Prdx1." (PMID 35126161, 2022). "Sulforaphane, as an antioxidant, induces the expression of antioxidant gene Prdx1, contributing to the recovery of psoriasis." (PMID 35126161, 2022).
pterygium (1 paper, 2022). A wedge-shaped fibrovascular lesion arising from the bulbar conjunctiva and extending to the cornea. "In comparison to healthy subjects (PRDX1, 2, and 5), it has been more frequently expressed in inflammatory conditions of the ocular surface and in the tear film associated with DE, as shown by pterygium biopsies (peroxiredoxin 1 and 2)." (PMID 35359431, 2022).
renal carcinoma (1 paper, 2022). A carcinoma arising from the epithelium of the renal parenchyma or the renal pelvis. "The compound was verified to induce apoptosis in renal carcinoma cells by reducing the ROS level caused by the upregulated peroxiredoxin 1 (PRDX1) and also demonstrated potent antitumor efficacy in renal carcinoma xenograft mice." (PMID 35601822, 2022).
Salmonella Infections (1 paper, 2015). Infections with bacteria of the genus SALMONELLA. "In our study, SOD and peroxiredoxin 1 resulted down-regulated after Salmonella infection in ileum at 1 and 2 dpi, whereas PKC was found up-regulated." (PMID 26389078, 2015).
transient ischemic attack (1 paper, 2020). A brief attack (from a few minutes to an hour) of cerebral dysfunction of vascular origin, with no persistent neurological deficit. "We looked in particular at the role of hs-CRP as a biomarker of inflammation, PRDX1 as a marker of oxidative stress and EPO as a potential neuroprotective mediator in predicting further ischemic events in patients who had experienced a transient ischemic attack (TIA) or lacunar stroke." (PMID 32733466, 2020).
vitiligo (1 paper, 2025). Generalized well circumscribed patches of leukoderma that are generally distributed over symmetric body locations and is due to autoimmune destruction of melanocytes. "We identified seven proteins (HEPHL1, PRDX1, DEFA1, CSGALNACT2, HERC4, NDC80, and SPHK2) causally associated with vitiligo risk." (PMID 40856249, 2025).
tumor (132 papers, 2010 to 2026). "Increasing evidence indicates that PRDX1 and its redox-associated pathways contribute to tumor progression and metastasis in multiple cancers, including breast, lung, and esophageal malignancies." (PMID 41019038, 2025). "On the other hand, loss of PRDX1 in macrophages restrains M2 polarization and enhances T‐cell‐mediated anti‐tumor immunity by promoting the secretion of inflammatory factors (IL‐1β and TNFα) via activation of JAK‐STAT1/NF‐κB signaling pathways." (PMID 41306557, 2025). "The up‐regulated genes in tumor‐infiltrating myeloid cells in RARα‐KO mice included Rnf128, Cd36, Nos2, Prdx1, Cd274, and H2‐Q4, associated with the immune‐activating phenotype." (PMID 40068101, 2025). "The PRDX1 gene, known for its association with oxidative stress, has been implicated as a tumor suppressor in several cancers." (PMID 38365790, 2024). "Widely expressed in tissues, PRDX1 serves as an intracellular antioxidant enzyme, implicated in various cellular processes including tumor suppression, apoptosis, and chaperone function." (PMID 39720522, 2024). "Microsatellite instability, tumor mutational burden, and T cell exclusion are more pronounced in HCCs with high PRDX1 expression." (PMID 37842089, 2023). "In short, PRDX1 deficiency generates metabolic changes in tumour cells, leading to DNA damage and tumour adaptation." (PMID 38067110, 2023). "The rescued overexpression of Prdx1 in HBXIP/Nrf2 axis-deficient cells restored the metastatic ability of tumor cells." (PMID 35027562, 2022). "According to the pooled results, high PRDX1 expression was associated with large tumor size, advanced TNM stage, and poor tumor differentiation." (PMID 33747258, 2021). "Elevated nuclear ROS on primary tissues isolated from the Prdx1−/− leads to increased DNA damage and tumor susceptibility." (PMID 32098329, 2020). "Meanwhile, PRDX1 overexpression was associated with tumor stage, lymphatic metastasis and differentiation." (PMID 31956363, 2020). "Our results also showed that the expression of PRDX1 was associated with tumor size, and was positively correlated with the expression of LINC00460." (PMID 31429766, 2019). "High levels of LINC00460 and PRDX1 expression were positively associated with lymph metastasis, pathological differentiation and tumor size in HNSCC patients." (PMID 31429766, 2019). "LINC00460 expression was positively associated with the pathological differentiation of tumors and with lymph node metastasis (p < 0.05), whereas PRDX1 expression was positively associated with tumor size (p < 0.05)." (PMID 31429766, 2019). "For example, the high expression of peroxiredoxin 1 (Prdx1) is associated with tumor development and overall survival of HCC patients and serves as a candidate biomarker for the screening and prediction of this malignancy." (PMID 31886163, 2019). "Overexpression of PRDX1 in BrCa has been observed to be positively associated with tumor grade and acted as dominant role in management of exogeneous oxidative stress." (PMID 31402980, 2019). "High PRDX1 expression was associated with low tumor grade (P <0.001), older age at diagnosis (P <0.001) and human epidermal growth factor receptor 2 (Her2) negativity (P = 0.001), while it displayed a borderline association with positive ER status (P = 0.05)." (PMID 25011585, 2014). "PRDX1 presence in carcinomas is associated with inhibition of apoptosis, equating to increased tumor survival." (PMID 21980378, 2011). "Notably, we discovered that PRDX1+LA-Macs represent a key tumor-enriched subset associated with unfavorable prognosis." (PMID 41601657, 2026). "PRDX1 deficiency significantly suppressed tumor proliferation,while PRDX1-OV promoted tumor growth." (PMID 40028362, 2025). "In addition, pathway enrichment analysis suggested that PRDX1 expression positively correlated with DNA repair, which is often considered to be inextricably linked to drug resistance in tumor cells." (PMID 40303499, 2025).